CD4 (CD4 molecule)
Diseases named in the same sentence as CD4 in open-access papers (continued):
Sharing a sentence is not in itself a finding about the gene and the disease.
cancer (continued). "For example, immunosuppressive interactions involving the PGE2, MIF and midkine (MK) gene products were more likely between cancer basal cells and CD4+ and CD8+ T cells in the older cohort." (PMID 41188599, 2025). "We further show that the observed cancer cell killing requires the presence of either CD8+ or CD4+ T‐cells and direct contact between GB and immune cells." (PMID 39535369, 2025). "Secondly, while CD4+ T cells, NK cells, and γδ T cells have been identified as key effector cells for ICB treatment in B2M-deficient cancers, the underlying mechanisms by which these cells mediate their cytotoxic effects remain to be fully elucidated." (PMID 40191187, 2025). "The literature indicates that the activation of T-reg cells can increase the risk of cancers such as HCC, with CD4+CD25+FoxP3+ T cells playing a significant role in this risk." (PMID 40881323, 2025). "This technology should greatly aid future studies to enhance our understanding of how interactions between cancer cells, CD4 T cells, and other immune or stromal populations influence disease pathology." (PMID 41256864, 2025). "One fundamental role of CD4+ T cells is to provide help to B cells for Ab production, but little is known about the role of Abs induced by cancer vaccines, particularly with peptide vaccines." (PMID 40543509, 2025). "In this study, we utilized recent advances in single‐cell eQTLs and comprehensively estimated the effects of gene expression dynamics during CD4+ T cell activation on common cancers." (PMID 41216857, 2025). "According to a recent study, CD4+ T cells can modify macrophages for enhanced cancer immunotherapy based on a stimulator of interferon genes (STING) signaling pathway." (PMID 40078996, 2025). "Recent studies report that CD4+ chimeric antigen receptor (CAR) T cells directly kill cancer cells by producing interferon (IFN)-γ6 and enhance the persistence and efficacy of CD8+ CAR T cells." (PMID 40107245, 2025). "In contrast, EPIC and TIMER showed fewer significant differences, with EPIC showing significance only in cancer-associated fibroblasts and macrophages, and TIMER in T cell CD4+, neutrophils, macrophages, and myeloid dendritic cells." (PMID 40349011, 2025). "In the immune cycle activity scores of LUAD, CHRDL1 is significantly positively correlated with Step2 cancer antigen presentation (cor = 0.472, p < 0.05) and Step4 CD4 T cell recruitment (cor = 0.435, p < 0.05)." (PMID 40230414, 2025). "The results showed that Hub-ANSDR.Sig is positively correlated with resting memory CD4+ T cells but negatively linked with CD8+ T cells and regulatory T cells (Tregs) in most cancer types." (PMID 40771813, 2025). "In CD4+ T cells, Fe-EGCG@RSL3 treatment diminished Jun/Fos-expressing stress response state T cells, which has been similarly identified as an immunotherapy resistance-related CD4+ T-cell subpopulation in single-cell analyses across 16 types of human cancers." (PMID 40530387, 2025). "We investigated the correlation between RNASEK expression and immune cells (B cells, CD8+ T-cells, CD4+ T-cells, macrophages, neutrophils, and dendritic cells) in six cancers, including BLCA, CHOL, ESCA, HNSC, LIHC, and THCA." (PMID 40546550, 2025). "Especially, Th1 and Th2 CD4+ T cells were most positively correlated with MKI67 expression in various cancer types." (PMID 40070823, 2025). "Previous observations underscore the critical role of CD4+ T cell activation in enhancing the effectiveness of cancer vaccines." (PMID 40543509, 2025). "Several aspects of CD4+ T cell biology suggest that this population can be effectively harnessed for cancer immunotherapy." (PMID 40543509, 2025). "Our study revealed strong positive correlations between CD68 expression and the infiltration levels of various TIICs, including B cells, CD4+ T cells, CD8+ T cells, macrophages, NK cells, and cancer-associated fibroblasts, across all DSC types." (PMID 40918116, 2025).
cancer (continued). "Recent evidence has shown that CD4+ and CD8+ T cell infiltration is associated with improved prognosis across multiple cancer types." (PMID 40277945, 2025). "This role has been demonstrated both in preclinical mouse models and in studies with CD4+ T cells obtained from cancer patients." (PMID 40430079, 2025). "There is a conflicting role for P-gp in cancer cells, which is expressed in the pro-tumor effect of MΦ2-macrophage and the anti-cancer effect of NK-cell and Th17/CD4+T cells." (PMID 40352931, 2025). "For quantitative assessment, we selected four tissue sections each for CXCL13 co-staining with CD4+ T cells, CD8+ T cells, and cancer-associated fibroblasts (CAFs)." (PMID 40352278, 2025). "A comprehensive analysis of CD4+ T-cell subsets, including Th1, Th2, Th17, Tregs, and Tfh, was conducted, along with their immunological roles in cancer." (PMID 40860882, 2025). "Using mIHC staining of the cancer sections, we identified CD4+ and CD8+ T cells around microvessels." (PMID 40038352, 2025). "Recently, a lower CD4:CD8 ratio (<0.5) has been shown in a large multi‐cohort study across Europe and Australia to be associated with an increased risk of several cancers." (PMID 40437996, 2025). "A pan-cancer analysis of PSAT1 suggested associations between PSAT1 levels and immune infiltration, specifically, of CD8+ T cells, CD4+ T cells, macrophages, neutrophils, and dendritic cells." (PMID 40612679, 2025). "NeoAg presentation to CD4+ T cells by pAPCs can produce a variety of therapeutic benefits in cancer." (PMID 40196575, 2025). "Successful therapeutic cancer vaccines rely on providing ample highly immunogenic antigens to the APCs, leading to a robust and lasting CD4+ T helper cell and CD8+ CTLs reaction." (PMID 40145100, 2025). "Clinical programmes should incorporate malignancy screening, especially for HPV-, HBV-, and HCV-related cancers—targeting older individuals and those with persistently low CD4 counts." (PMID 41295583, 2025). "This research revealed strong positive correlations of ADM with CD4+ T cells, macrophages, and B cells in cancers such as LUAD and MESO, supporting ADM’s role in recruiting and activating immune cells." (PMID 40529377, 2025). "Although the CD8+ T cell is the main cytotoxic effector cell in anti-virus and -cancer responses, CD4+ T cells can also kill." (PMID 40333248, 2025). "Such expansion to HLA-II would enable comprehensive profiling of both CD8+ and CD4+ T cell responses in cancer and infectious diseases." (PMID 40721532, 2025). "To uncover potential features of CD4+ T-cell dysfunction in cancer and parallels with CD8+ T-cell exhaustion, we used the same marker profiles to investigate CD4+ T-cell subsets, which were identified by the expression of Tcf1/7 and TOX, respectively." (PMID 40897819, 2025). "For example, IL-22 produced by tissue-resident iNKT cells or CD4+TRM cells promotes cancer metastasis at different stages." (PMID 39820040, 2025). "CTLs (CD3+CD8+ T cells) and helper T cells (CD3+CD4+ T cells) are essential to against cancer cells, triggering an adaptive immune response." (PMID 40051340, 2025). "Cluster #22398, which was prevalent in COP (COP vs. malignancies: 11.9 ± 0.6% vs. 1.7 ± 0.9%), was characterized by the expression of CD4+ CD16+ HLA-DR+ CD44hi ST2+ TIM-3hi PD-L1hi PD-L2hi." (PMID 39860323, 2025). "The importance of the CD4:CD8 ratio in the T cell infusions for patients receiving immunotherapy for cancer treatment has been highlighted by several previous reports, with a ratio of 1:1 commonly proposed to drive optimal clinical responses." (PMID 40934229, 2025). "Overall, except for UCS, ITGA4 expression showed significant correlations with the infiltration of multiple immune cell types, especially macrophages, CD8+ T cells, and CD4+ T cells, in most cancers." (PMID 40012546, 2025).
cancer (continued). "Overall, [64Cu]Cu-NOTA-IAB41 enables real-time, quantitative immuno-PET imaging of CD4-positive T-cell distribution in vivo, offering a promising approach for studying cancer immunotherapies and neuroinflammatory processes." (PMID 41019666, 2025). "One of the critical hurdles in cancer immunotherapy is the ability to effectively deliver therapeutic agents to CD4+ T cells within the TME, which is highly immunosuppressive." (PMID 40860882, 2025). "CD4+ T cells support CD8+ T cell activation, enhancing cancer cell elimination, and their high numbers are also associated with improved clinical outcomes." (PMID 40136652, 2025). "Third, while many clinical cancer mRNA vaccines encode both CD8+ and CD4+ T-cell epitopes, the observed immune responses are predominantly mediated by CD4+ T cells rather than CD8+ T cells." (PMID 40629076, 2025). "In this context, it has been reported that CAF‐secreted lactic acid is uploaded by CD4+ T cells, favoring their polarization to Treg and reducing the antitumoral Th1 subpopulation, ultimately promoting cancer cell invasiveness." (PMID 40569831, 2025). "CD8+ T cells can directly eliminate cancer cells expressing tumor antigen, while CD4+ T cells coordinate the entire immune response by secreting cytokines." (PMID 39744225, 2025). "In some cancers including HNSCC, intratumoral CD4+ T cells exhibit cytotoxic phenotypes capable of directly killing cancer cells, similar to CD8+ T-cells, while performing helper functions." (PMID 40392349, 2025). "By stimulating CTLs and boosting immune responses through the generation of cytokines, HTLs, especially CD4+ T cells, are essential in the destruction of cancer cells." (PMID 40453095, 2025). "Functional research on cancer cell lines and CD4+, CD8+ lymphocytes will be carried out as part of the current project to ultimately confirm the immunomodulatory characteristics of the novel peptide inhibitors." (PMID 40245195, 2025). "By combining cutting-edge nanotechnology with immunological insights, this work highlights the transformative potential of nano-immunotherapy for targeting CD4+ T-cells in cancer treatment." (PMID 40860882, 2025). "They demonstrated that cancer-specific CD4+T cells exhibited increased expression of effector cytokines when stimulated by apCAFs." (PMID 39897591, 2025). "As data integration was run again on the CD4+ T cell dataset after subsetting from the pan-cancer T cell atlas, we checked its quality by dimension reduction." (PMID 40260243, 2025). "CellChat analysis revealed that the exhaustion phenotype of CD4+ (Treg, CH25H+, and CCR7+ naive) and active CD8+ (TEM and MAIT) cells was associated with significant intercellular communication with the cancer‐pre cells we identified." (PMID 40860436, 2025). "The findings indicate that among patients with pan-cancer, older age, a higher absolute count of CD4+CD38−T cells in peripheral blood, and a lower absolute count of CD4+CD28−T cells are associated with a heightened risk of developing CRF." (PMID 41018226, 2025). "Recent studies have suggested that many immune cell eQTLs, including eQTLs from CD4+ T cells, showed heterogeneous effects across cell types, but the influence of such heterogeneous effects on cancers was unclear." (PMID 41216857, 2025). "Neighbor enrichment scores and cluster co-occurrence analysis indicated that VPS25high cancer cells were significantly more distant from immune cells, particularly CD4+ and CD8+ T cells, compared to their VPS25low counterparts." (PMID 40149859, 2025). "In patients (benign and malignant), the range was 20% to 75%, with a tendency to have more CD4+ T cells in those with malignant tumors." (PMID 40870871, 2025). "Immune gene analysis of carcinoma patient showed an increase in neutrophils, activated mast cells, and memory CD4 T cell signatures, along with a decrease in monocytes and follicular helper T cells 2 weeks post-treatment." (PMID 40386779, 2025).
cancer (continued). "In HPV-positive carcinomas, we observed significant spatial co-localization between cDC2-enriched regions and CD4+ T cell zones." (PMID 41035636, 2025). "CCL17 is a known STAT6 transcriptional target and chemoattractant that recruits various CCR4 + immune cells—such as CD8+ or CD4+ T-cells, and macrophages—in murine and canine cancer models, in addition to human tumors." (PMID 38285120, 2024). "CD8+ T cells are known for their cytotoxic activity against cancer cells, while CD4+ T cells aid in orchestrating immune responses." (PMID 38560573, 2024). "The results suggested that memory CD4 + T cells and Macrophage M2 cells were positively related to the anoikis-related signature in pan-cancer, while Treg cells were inversely related." (PMID 38310291, 2024). "CD8+ T cells and CD4+ effector T cells have demonstrated anti-cancer potential, while regulatory T cells (CD4+ CD25+ Tregs) have been shown to be able to contribute to the attenuated immune response exhibited in cancer." (PMID 38893120, 2024). "In such cases, CD4+ T cells mainly play an indirect function in helping effector T cells kill cancer cells." (PMID 39493763, 2024). "The conditioned medium from cancer organoid #2 significantly increased the CD3+/CD4+/FOXP3+ Treg subset compared to that of the control, while knocking out galectin‐9 suppressed this subset." (PMID 38528665, 2024). "ACT with TILs is a personalized cancer treatment which consists of ex vivo expansion of autologous tumor infiltrating CD4+ and CD8+ T lymphocytes and their reinfusion in the same patient after lymphodepletion." (PMID 39114660, 2024). "The effectiveness of therapeutic cancer vaccines primarily relies on the capacity of DCs to display TAs that contain CD4+ and CD8+ T-cell proteins." (PMID 38793749, 2024). "Single-nuclear RNA sequencing suggested that TGF-β-TRAP modulates cancer-associated fibroblast (CAF) heterogeneity and suppresses neutrophil degranulation and CD4+ T cell response to neutrophil degranulation." (PMID 39298276, 2024). "Multiple cancers display an abnormal PC metabolism, which incited us to evaluate this lipid pathway in our mAITL CD4 + PD-1high cells." (PMID 38321568, 2024). "In our patient, the CD4 cell count prior to cancer diagnosis was 754 cell/μl and he had an undetectable viral load." (PMID 40190535, 2024). "Single-cell dataset analysis further indicated that cancer stem cells, CD4+ memory cells, regulatory T cells, NK cells, fibroblasts, and neurons participate in the regulation of related genes, with GZMB serving as a marker for NK cells." (PMID 38846945, 2024). "The clinical implication of this finding is that the CD4:CD8 ratio should be taken into account during adoptive transfusion of CAR- or TCR-T cells as anti-cancer treatment to improve the effect of adoptive reinfusion and reduce inflammatory cytokine storms." (PMID 38755254, 2024). "Despite less understood than CD8+ T cells in anti-cancer function, the CD4+ T cell subset has been recently demonstrated to be protective against cancer progression likely by enhancing tumoricidal activity of other antitumor effector cells subsets." (PMID 38650951, 2024). "For example, EMT, hypoxia, and TGF-β signaling have all been shown to be inversely correlated with CD8+ and/or CD4+ T cell infiltration in various cancer types." (PMID 38398074, 2024). "With a recent interest in the field, CD4+ T cell-derived exosomes are considered promising agents that can mediate antitumor effects in cancer immunotherapy." (PMID 38172594, 2024). "Although long-term CD4+ T cell compartment depletion leads to obvious defects in both T and B cell adaptive immune responses, transient CD4+ T cell depletion has been clinically tested in cancer and other disease states using an ɑCD4 antibody." (PMID 38429261, 2024).
cancer (continued). "Results showed that naïve patients had high levels of CD137+ T cells (total, CD8, and CD4) compared to platinum-doublet chemotherapy-treated patients, demonstrating that chemotherapy negatively impacts the immune activatory profile of cancer patients." (PMID 38570798, 2024). "TGFβ derived from cancer cells has been proven to promote the transformation of CD4+ T cells into Treg cells and exclusion of T cells." (PMID 38694917, 2024). "We observed the ITPRIPL1 expression is strongly associated with activated memory CD4+ T cells, CD8+ T cells, regulatory T cells (Tregs), M1 macrophages, NK cells and activated dendritic cells in some cancer types." (PMID 39211744, 2024). "In general, however, CD44 was positively related to infiltration of macrophages, neutrophils, and CD4+ memory T cells, but negatively related to T follicular helper cells, B cells, NK cells, and regulatory T cells (Tregs) in most cancers." (PMID 38590654, 2024). "The patient cohort selected for enrichment of CD4 + leukocytes included 30 male participants from the Epidemiology for health study (EpiHealth) and 2 males from the Uppsala-Umeå Comprehensive Cancer Consortium (UCAN)." (PMID 38443832, 2024). "Cytotoxic CD8 (+) T lymphocytes can directly kill cancer cells, while CD4 (+) T lymphocytes are involved in the activation and inhibition of CD8 (+) T lymphocytes." (PMID 38736875, 2024). "In this large prospective multinational cohort study of ART treated individuals who were followed between 2012 and 2020, a low CD4:CD8 ratio was associated with significantly higher risk of ADM and infection-related cancers independent from CD4 cell counts." (PMID 38092042, 2024). "In our study, most children had normal IgG levels and normal CD19, CD4, and NK counts by 4 months post cancer treatment." (PMID 38767518, 2024). "Inclusion of universal CD4 epitopes in murine cancer vaccines resulted in improved effector functions of antigen-specific CD8+ T cells and increased survival." (PMID 39040850, 2024). "For example, the sensitivity analysis shows how increasing T cell exhaustion by cancer cells diminishes the CD8 to CD4 ratio." (PMID 38858306, 2024). "We also verified a strong positive correlation between SELENOI expression and CD4+ T cell presence in most cancer types." (PMID 39669976, 2024). "Immune cell infiltration analysis revealed that CD4+T and CD8+T cells were enriched mainly in the low-risk score group, whereas macrophage M0 and cancer-associated fibroblast cells were highly infiltrated the high-risk model group." (PMID 38341588, 2024). "Tregs, a subset of CD4+ T cells, are closely related to the pathogenesis of cancer and express the transcription factor FoxP3." (PMID 39605905, 2024). "His CD4+ T cell count prior to the cancer diagnosis was 754 cells/μl with undetectable HIV RNA (viral load)." (PMID 40190535, 2024). "Collectively, we uncovered an unappreciated paracrine mechanism of how Bcl6 promotes cancer progression and highlighted the role of CD4+T cells in HCC immune surveillance." (PMID 38956432, 2024). "The cancer vaccination aims to increase the number of antigen-specific CD4+ and CD8+ T cells capable of recognizing and eliminating tumor cells." (PMID 39092051, 2024). "In TME, CD4+T cells are recruited to cancer cells by various chemotactic factors and adhesion molecules." (PMID 39493763, 2024). "The findings indicated that T cell NK, macrophage, dendritic cell, cancer associated fibroblast, and monocyte were positively correlated with LRRS, while basophil and T cell CD4+ memory were negatively correlated with LRRS." (PMID 39749343, 2024). "In another set of studies, an IL-2/CD25 fusion protein with selectivity towards the high-affinity IL-2R was shown to better amplify cancer-vaccine activated CD4+ and CD8+ T cell responses compared to WT IL-2 treatment." (PMID 39114660, 2024).